LEPR (leptin receptor)
Diseases named in the same sentence as LEPR in open-access papers (continued):
Sharing a sentence is not in itself a finding about the gene and the disease.
Obesity (continued). "Many hepatic miRNAs located in the miR-379/miR-544 cluster were augmented in leptin-receptor-deficient type 2 mice and genetic mutation of this cluster in mice showed resistance to high-fat-diet-induced obesity with lower hypertriglyceridemia and steatosis." (PMID 36674935, 2023). "In the current study, the Zucker rat (fa/fa) is used as a model of obesity and is characterized by a mutated leptin receptor." (PMID 38036455, 2023). "The Zucker rat has a mutation in the gene encoding the leptin receptor and as a result displays hyperphagia and obesity." (PMID 38036455, 2023). "Obese Zucker rats (fa/fa), a popular genetic obesity mode, become obese because of increased food intake secondary to a genetic leptin receptor deficiency, which results in a low-satiety response." (PMID 37298051, 2023). "Similar to ob/ob mice, db/db mice are a model of congenital obesity and type 2 diabetes due to a mutation in the db gene on chromosome 4, which causes abnormal transcription of leptin receptor." (PMID 37723622, 2023). "Among numerous obesity-related genes, mutations in genes of the leptin receptor, G protein-coupled receptor 24, and melanocortin receptors 3 and 4 are argued to be the main factors of the development of monogenic obesity in humans." (PMID 36984693, 2023). "In the fa/fa Zucker rat model of obesity and diabetes caused by leptin receptor deficit, CCN2 mRNA and protein were enhanced by 35 weeks of age in fa/fa rats but not in lean fa/fa littermates." (PMID 37629004, 2023). "High-sugar diet-induced diabetes and genetically diabetes (db/db) mice can cause obesity and dyslipidemia by either microbiota imbalance or deficiency of leptin receptor." (PMID 37400924, 2023). "Genes implicated in severe and early-onset obesity-coding receptors or signaling components including LEPR (human, mice), MC4R, NTRK2, SIM1, SH2B1, MRAP2, KSR2, and ADCY3 (human) were revealed." (PMID 36984693, 2023). "Here, we investigated the influence of obesity and hyperglycaemia on osseointegration using a novel, leptin receptor-deficient animal model, the Lund MetS rat." (PMID 37730735, 2023). "Leptin (ob/ob) or leptin receptor (db/db) deficient mice and humans developed pronounced hyperphagia and obesity, suggesting leptin is a key player in the control of feeding and energy balance." (PMID 38027481, 2023). "DB/DB is a spontaneous transgenic mouse model of type 2 diabetes with leptin receptor point mutation, which develops symptoms of obesity, insulin resistance, and hyperglycemia." (PMID 37010266, 2023). "Of note, selective deletion of LepR in LH neurons in adult mice causes obesity only under HFD conditions, reinforcing the notion that the primary target of leptin is context-dependent." (PMID 37547309, 2023). "The epidermal growth factor receptor (EGFR) tyrosine kinase inhibitor decreased obesity in a murine model of leptin receptor-deficient T2DM." (PMID 36747287, 2023). "In this study, Slc7a5 deficiency led to leptin insensitivity in LepR-expressing neurons and decreased sympathetic outflow prior to the onset of obesity." (PMID 36862514, 2023). "Mice lacking LAT1 (encoded by solute carrier transporter 7a5, Slc7a5) in LepR-expressing neurons exhibited obesity-related phenotypes and higher bone mass." (PMID 36862514, 2023). "In line with the development of (functional) leptin resistance in End.LepR-KO mice, obesity was associated with elevated leptin levels." (PMID 37217565, 2023). "Monogenic forms of obesity due to deficiencies in leptin and leptin receptor genes are characterized by early-onset of rapid weight gain, hyperphagia and insulin resistance, frequent infection, and pituitary hormone deficiency." (PMID 37329217, 2023). "Adult female carriers of the T allele in LEPR Ser (T) 343 Ser (C) polymorphism showed a stronger predisposition to obesity, while carriers of the C allele demonstrated greater weight loss in response to a low-caloric diet intervention compared to non-carriers." (PMID 36986146, 2023).
Obesity (continued). "To explore cBIN1 expression in hearts with diabetic cardiomyopathy, we used leptin receptor–deficient Leprdb (db/db) mice, which is a common obesity-associated T2DM model." (PMID 37639557, 2023). "The db/db mice have spontaneous mutations in leptin receptor and mimics the pathophysiology of human type 2 DM including obesity and late stage β cell atrophy." (PMID 37887287, 2023). "Together, these results suggest that Slc7a5 deficiency in LepR-expressing neurons exacerbates HFD-induced obesity and metabolic dysfunction." (PMID 36862514, 2023). "This has a point mutation in the leptin receptor gene, which leads to obesity, insulin resistance, and infertility." (PMID 37109170, 2023). "The db/db mice have a mutation in the leptin receptor, and display hyperphagia, and consequently develop obesity, hyperglycemia and insulin resistance, resembling key features of human T2D." (PMID 36901964, 2023). "Clinically, the initial descriptions of young patients with obesity consequent to LEP or LEPR deficiency were rather similar." (PMID 37659411, 2023). "Mutations in the leptin receptor produce a monogenic form of obesity typified by hyperphagia and weight gain, with a prevalence of around 3% of children with obesity." (PMID 36674935, 2023). "Mutations in the genes encoding the MC4R, leptin, and leptin receptor are commonly reported in various populations to cause monogenic obesity." (PMID 37329217, 2023). "Diet-induced obesity and leptin receptor-deficient db/db mice lack CLK2 signal in the hypothalamic neurons." (PMID 37635967, 2023). "Leptin-deficient OB/OB mice and leptin receptor-deficient db/db mice are two monogenic rodent models that have been widely studied and used as preclinical models that mimic the conditions of obesity and T2D development." (PMID 37650104, 2023). "Rapid deletion of LepR from AgRP neurons caused an obesity phenotype which can be rescued by blockage of GABAA receptor in the DMH." (PMID 37043384, 2023). "Slc7a5 deficiency caused sympathetic dysfunction and leptin insensitivity in LepR-expressing neurons before obesity onset." (PMID 36862514, 2023). "The most direct evidence for a role of leptin in establishing the low-grade systemic inflammatory response associated with obesity is that WAT inflammation was strongly reduced when LepR were knocked out in mouse leukocytes." (PMID 36769012, 2023). "In single-arm, open-label, multicenter, phase 3 trials, subcutaneous once-daily setmelanotide was evaluated for efficacy and safety in individuals with severe obesity due to either POMC deficiency or LEPR deficiency." (PMID 37937009, 2023). "Relevant research results are obtained by building 2 common models of severe obesity (leptin receptor deficient db/db mice and leptin deficient ob/ob mice), whereas, our background mice were C57BL/6." (PMID 37370070, 2023). "In this work, we used the Lund MetS rat, which mimics metabolic syndrome in humans by developing severe obesity, hyperglycaemia, and high blood pressure in addition to elevated cholesterol and triglyceride levels due to a leptin receptor mutation." (PMID 37730735, 2023). "Leptin receptor-deficient (db/db) mice are similar to ob/ob mice in terms of obesity, but they show less steatosis than ob/ob mice." (PMID 37373143, 2023). "The female patients demonstrated that LEPR 223QR and LEPR 223RR were associated with lower obesity risk, with genotype RR showing less average body weight." (PMID 36551995, 2022). "Various mutations in the LEPR gene leading to leptin signaling deficiency through disruption in the LEPR function resulted in many cases in obesity/diabetes phenotypes in humans and rodents." (PMID 35650533, 2022). "The increased expression of the leptin receptor results in more active binding to leptin, whose elevated secretion by adipocytes is associated with the increased obesity risk." (PMID 35207726, 2022).
Obesity (continued). "Deficiencies in leptin or LepR signaling, or leptin resistance can develop in response to inflammation, endocrine disorders, lipodystrophy, or obesity, which progresses to glucose intolerance and insulin resistance." (PMID 35159237, 2022). "In this study, we used db/db mice, a model of spontaneous obesity due to the leptin receptor deficiency, to explore the antiobesity effect of JLD." (PMID 35647185, 2022). "Although KKAy mice have been widely used in mouse model of obesity further assessment using another obesity model mice, e.g. leptin-deficient ob/ob mouse or leptin receptor deficient db/db mouse, can validate our results." (PMID 35949596, 2022). "In this study, we utilized obese mouse models driven by a high-fat diet, the leptin-deficient ob/ob mouse, and the leptin receptor deficient db/db mouse to determine the effect of obesity in endometriosis development." (PMID 36140261, 2022). "Previously, it has been reported that the genetic variants in ADIPOQ, CETP, FTO, LEP, and LEPR genes are strongly correlated with obesity and associated metabolic complications in different ethnicities of the world." (PMID 36126070, 2022). "The commonly used leptin deficient (ob/ob) or leptin receptor deficient/leptin resistant (db/db) background has been commonly used to replicate obesity involvement in MAFLD." (PMID 36499091, 2022). "Obesity and diabetes often go hand in hand in clinical settings, and therefore animals that are deficient for leptin and the leptin receptor are an elegant way of modeling such a setting." (PMID 35628192, 2022). "The missense mutation in the leptin receptor gene (fa/fa) in ZDF rats allows the study of T2DM in the condition of obesity." (PMID 36290422, 2022). "Mutations in the leptin receptor gene, for example, have been associated with obesity and pituitary dysfunction." (PMID 36241774, 2022). "The LEPR gene encodes for the leptin receptor and mutations were associated with obesity and pituitary malfunction." (PMID 36362270, 2022). "Zucker fatty diabetes mellitus (ZFDM) rats harboring the missense mutation (fa) in a leptin receptor gene have been recently established as a novel animal model of obesity and type 2 diabetes (T2D)." (PMID 35457048, 2022). "We intraperitoneally (i.p.)injected leptin receptor-deficient (db/db) obesity model mice with phosphate-buffered saline (PBS) or 0.5 μg of recombinant IL-33 (rIL-33) to activate ILC2s for 5 consecutive days." (PMID 36109558, 2022). "Mutation in the leptin receptor gene causes hyperphagia in this rat model and drives the metabolic, prediabetic, consequences, thus being similar to a chronic model of obesity." (PMID 38938664, 2022). "Leptin receptor-deficient db/db mice developed characteristics of hyperphagia, an extreme blood sugar level, high lipid levels, severe obesity, and infertility, whereas an MCT diet in that animal model improved spermatogenesis and spermiogenesis." (PMID 35223950, 2022). "Further, there is controversy regarding genetic obesity models in the field such as the effect of leptin receptor mutations." (PMID 35544474, 2022). "ZF and ZDF rats have leptin receptor mutations that lead to hyperphagia, overnutrition, and development of obesity and T2D." (PMID 36276822, 2022). "It has been established that LEPR polymorphism is linked to obesity, insulin resistance, and dyslipidemia, and that serum leptin in PCOS women is elevated due to a high quantity of adipose tissue." (PMID 36522620, 2022). "Mice homozygous for the leptin receptor mutation that results in the development of obesity show a reduction in Bacteroidetes and an increase in Firmicutes compared to their wild-type siblings when fed the same diet." (PMID 35432282, 2022). "Leptin signals through the different leptin-receptor (LEP-R) isoforms, and loss of leptin as well as the leptin-receptor function, has been linked to extreme obesity, immune dysfunction and infertility." (PMID 36289764, 2022).
Obesity (continued). "There are multiple underlying causes of obesity phenotypes in LEPR mutants, including hyperphagia, increased lipogenesis, or increased feed efficiency." (PMID 35650533, 2022). "ZFDM-Leprfa/fa (Homo) rats develop obesity due to overeating caused by a dysfunction of the leptin receptor." (PMID 35457048, 2022). "The lead variant on chromosome 1 (rs11208712) is intergenic and the closest gene is leptin receptor (LEPR), a gene linked to obesity." (PMID 36088317, 2022). "ZDF rats are characterized by hyperphagia and obesity leading to diabetes mellitus due to a missense mutation in the gene coding the leptin receptor (fa/fa)." (PMID 36290422, 2022). "Leptin receptor-deficient Leprdb/db mice develop significant obesity, fasting hyperglycemia, and hyperinsulinemia and are a model for type 2 DM." (PMID 36121152, 2022). "The Zucker Fatty (ZF) rats are an animal model which carries a spontaneous mutation in the leptin receptor gene, causing obesity and insulin resistance." (PMID 36276822, 2022). "Individuals with proopiomelanocortin (POMC) or leptin receptor (LEPR) deficiency are young and experience severe obesity, hyperphagia, and comorbidities, which can impair quality of life (QOL)." (PMID 35123544, 2022). "This mouse model carries a loss of function mutation in the leptin receptor gene and provides a well-established model of obesity-induced type 2 diabetes." (PMID 35725987, 2022). "Several studies that have investigated the association of leptin and LepR with obesity patterns have indicated several limitations with confounding factors, such as environment, psychological state, food habits, etc.." (PMID 35886710, 2022). "These mice harbor a mutation in the leptin receptor gene, which results in obesity and mimics type 2 diabetes." (PMID 36367946, 2022). "In numerous populations and age groups, the effect of LEP and LEPR polymorphisms on the risk of obesity has been well-documented." (PMID 35886710, 2022). "In that study of db/db mice that develop diabetes because of leptin receptor mutation-induced hyperphagia with associated obesity and hyperinsulinemia and later hypoinsulinemia, 10 mg MCC950 per kg body weight was administered i.p. twice per week for 12 weeks." (PMID 35048962, 2022). "For example, the Zucker rat strain, which bears a mutation in the leptin receptor gene, is sugar metabolic deficient and insulin resistant and thus, serves as a spontaneous genetic obesity model." (PMID 35198334, 2022). "Obesity and enhanced bone metabolism are linked to adipokines like leptin, and obese rats with elevated leptin receptor genes experience spinal ligament ossification, according to research." (PMID 36036007, 2022). "In this study, there was a positive correlation association in LEP G2548A and LEPR Q223R variants in obese subjects, indicating that these polymorphisms can increase obesity risk." (PMID 36551995, 2022). "A clear illustration of this is the Zucker Diabetic Fatty (ZDF) rats, a widely used model of obesity caused by the mutation of the leptin receptor gene (Lepr, also known as Fa)." (PMID 36505380, 2022). "Only a few studies have reported mutations in LEPR associated with obesity, although early-onset obesity involving LEPR mutations is less prevalent." (PMID 35563103, 2022). "Mutations in LEPR can result in obesity with additional features, such as severe obesity, alteration in immune function, hypogonadism, and hypothyroidism." (PMID 36052737, 2022). "LEPR has six isoforms (A–F), which, along with leptin, are associated with obesity, with the first LEPR mutation being reported in North Africa (c.2598 + 1G>A)." (PMID 35563103, 2022). "Animal models of obesity and T2D diabetes such as leptin receptor deficient db/db and leptin deficient ob/ob mice were also treated with DAPA." (PMID 35180212, 2022). "In animal models, a genetic LepR deficiency in Leprdb mice manifests with obesity, diabetes, hyperglycemia, insulin resistance, as well as aberrant immune responses and reproduction." (PMID 35159237, 2022).
Obesity (continued). "On the other hand, leptin receptor-deficient db/db;ApoE–/– have demonstrated accelerated atherosclerosis accompanying hyperglycemia, obesity, hyperinsulinemia and dyslipidemia vs. age-matched ApoE–/– mice." (PMID 36505365, 2022). "Altered leptin levels in obesity and anorexia have also been associated with leptin and leptin receptor gene polymorphism." (PMID 35886710, 2022). "We surgically induced endometriosis in 8-week-old db/+ or db/db female recipients of donor uterine fragments from control db/+ or db/db to determine the effects of obesity with leptin receptor deficiency on endometriosis." (PMID 36140261, 2022). "In the group of middle-aged patients (age ≤60 years), the G/G genotype in the LEPR gene (rs1137100) was associated with a fourfold increased risk of obesity (OR = 4.23, 95% CI = 1.74–10.28, p = 0.03)." (PMID 35207726, 2022). "Homozygous mutations of the leptin receptor lead to increased leptin levels and obesity along with impaired pubertal development and reduced levels of growth hormone and TSH." (PMID 36432490, 2022). "Two pivotal Phase 3 trials explored the effect of setmelanotide on body weight and hunger in individuals with obesity due to POMC (NCT02896192) or LEPR (NCT03287960) deficiency." (PMID 35123544, 2022). "We further performed stratified analysis to determine the association between LEP/LEPR polymorphisms and breast cancer risk according to obesity indicators including BMI and WHR." (PMID 35223490, 2022). "POMC deficiency and LEPR deficiency are caused by genetic variants in the leptin-melanocortin signaling pathway and are characterized by early-onset severe obesity and hyperphagia." (PMID 35123544, 2022). "LEPR gene polymorphism is associated with early onset of severe obesity and hyperphagic eating behavior." (PMID 35207726, 2022). "Genetically speaking, over 600 genetic locus are associated with obesity, and many studies have focused on the LEPR, MC4R, and FTO genes." (PMID 35624438, 2022). "Hypoxic treatment was previously shown to aggravate endothelial damage by down-regulating the PPARγ pathway in the leptin receptor deficient db/db mice, which are used to model obesity and insulin resistance." (PMID 36147493, 2022). "Leptin-receptor-deficient (db/db) mice are widely used as diabetic animal models accompanied by obesity and liver steatosis, automatically generating hyperglycemia with insulin resistance under standard feedings." (PMID 36077090, 2022). "The primary cause for obesity in Zucker (fa/fa) rats is due to the mutation in the leptin receptor gene (fa) which is inherited by the rats as an autosomal recessive trait." (PMID 35432282, 2022). "This 80 kb deletion is consistent with previous observations that heterozygous human carriers of leptin or LEPR mutations are predisposed to overweight and obesity." (PMID 35456010, 2022). "The leptin-deficient ob/ob mouse and the leptin receptor deficient db/db mouse are the most commonly used genetically engineered animal models of obesity." (PMID 36140261, 2022). "Similar findings that exogenous GDF15 reversed hyperphagia and obesity were also shown in leptin receptor-deficient ZF rats." (PMID 35202387, 2022). "A mouse line deficient in leptin receptor that displayed several hallmarks of diabetes, including hyperglycemia, obesity, and impaired wound healing, was used in this study." (PMID 34575535, 2021). "While the effect on body weight was small compared with complete loss of leptin receptors, the obesity was greatly exacerbated when the VMH LepR knockout mice were switched to a high-fat diet." (PMID 34265067, 2021). "The association of LEPR gene with pathologies, including obesity, diabetes, pregnancy complications [28, –, 30], cancer was investigated in several populations." (PMID 33245096, 2021). "Single nucleotide mutations (SNP’s) of the leptin receptor (LEPR) gene that result in a premature termination of the intracellular domain of the protein have been considered responsible for obesity." (PMID 35052401, 2021).